CXCL12 (C-X-C motif chemokine ligand 12)
Diseases named in the same sentence as CXCL12 in open-access papers (continued):
Sharing a sentence is not in itself a finding about the gene and the disease.
papillary thyroid carcinoma (7 papers, 2017 to 2025). "For example, in papillary thyroid carcinoma (PTC), senescent tumor cells enhance the invasive potential by switching on SASP through CXCL12/ CXCR4C76." (PMID 32566256, 2020).
pulmonary diseases (7 papers, 2012 to 2024). "CXCL12 is well-implicated in fibrocyte trafficking in fibrotic lung disease." (PMID 38935158, 2024). "The role of the chemokine ligand CXCL12 in trafficking of fibrocytes and phenotype of lung disease was examined in the animal model." (PMID 22442712, 2012). "This suggests a correlation between serum SDF-1/CXCL12 and pulmonary diseases." (PMID 27309347, 2016).
rectal cancer (7 papers, 2016 to 2025). A primary or metastatic malignant neoplasm that affects the rectum. "Blocking vascular endothelial growth factor (VEGF) has been reported to lead to tumor hypoxia in local rectal cancer, which may lead to an increase in circulating CXCL12 associated with metastasis." (PMID 34976180, 2022). "The expression of the two markers FAP-α and C-X-C motif chemokine ligand (CXCL) 12, known as stromal cell-derived factor 1 (SDF-1), was positively associated with poor clinical outcomes in rectal cancer patients who underwent neoadjuvant chemoradiation." (PMID 33803229, 2021). "In addition, CXCL12 mediates the progression of rectal cancer by promoting the retention of neutrophils in tumors and increasing their interactions with CD8+ T cells." (PMID 37575253, 2023). "In addition, three hub genes, including SST, SSTR2, and CXCL12, were significantly downregulated in the rectal cancer tissues." (PMID 34269159, 2021). "Besides CXCL1, CXCL2, and CXCL3, we mined seven other hub genes related to rectal cancer, including SAA1, AGT, GNG4, SST, SSTR2, GAL, and CXCL12." (PMID 34269159, 2021). "DCN and CXCL12 were overexpressed by our chemo/CRT remodelled CAFs (CAFs 3 and 4), CAF populations like these were found to be expanded in NAC (neo-adjuvant chemotherapy) responsive rectal cancers and are known to activate anti-cancer immunity and suppress tumour progression." (PMID 40640495, 2025).
cerebral infarction (6 papers, 2014 to 2023). An ischemic condition of the brain, producing a persistent focal neurological deficit in the area of distribution of the cerebral arteries. "Moreover, the activated platelets can release CXCL12 by themselves, resulting in an augmentation in the synergistic effect with GPIb/IX/V, which may cause thrombus formation in acute occlusive angiopathies, such as brain infarction and acute coronary syndrome." (PMID 37298667, 2023). "The present study takes advantage of the important role of the CXCL12/CXCR4 axis in the recovery of cerebral infarction." (PMID 33381162, 2020). "Additionally, hours after cerebral infarction, CXCL12 expression was elevated in both astrocytes and endothelial cells." (PMID 33381162, 2020).
CNS lymphoma (6 papers, 2013 to 2022). "In the perivascular TME, CXCL9 can form heterocomplex with B-cell chemoattractant CXCL12 to enhance CXCL12-induced CD8+ T cell as well as malignant B cell recruitment toward BV walls in the primary central nervous system lymphomas." (PMID 34179005, 2021). "A study directly supporting the idea that the activity of heterocomplexes can be relevant also in cancer was performed in our laboratory, showing the role of the CXCL9/CXCL12 heterocomplex in primary central nervous system lymphoma (PCNSL)." (PMID 30319638, 2018). "In primary CNS lymphoma, pericyte-derived CXCL9 and CXCL12 increase tumor-infiltrating lymphocytes, including CD8+ T cells." (PMID 35439170, 2022). "Further, we provide evidence that APRIL and BAFF induce chemotaxis of systemic and CNS lymphoma cell lines, confirming previously published results showing that BAFF increases the chemotactic response of human B cells to CXCL12, CXCL13, and CCL21 in vitro." (PMID 31615554, 2019). "The CXCL12 and CXCL13 CSF/serum ratios were roughly similar to those reported in a recent analysis of CNS lymphoma." (PMID 24278364, 2013). "While neither serum nor CSF CXCL12 levels differed between the CNS lymphoma patients and controls, CSF CXCL13 concentrations were significantly higher in the CNS lymphoma cohort, even as serum CXCL13 levels were consistently low in both groups." (PMID 28603659, 2016).
epilepsy (6 papers, 2019 to 2023). A brain disorder characterized by episodes of abnormally increased neuronal discharge resulting in transient episodes of sensory or motor neurological dysfunction, or psychic dysfunction. "More importantly, the overexpression of CXCL12 mitigates the increased epilepsy susceptibility and abnormal behaviors in adolescent offspring." (PMID 38129829, 2023). "Taken together, overexpression of CXCL12 can rescue the increased epilepsy susceptibility and ameliorate abnormal behaviors in Sevo group offspring mice." (PMID 38129829, 2023). "Next, we examined whether overexpression of CXCL12 could rescue the increased epilepsy susceptibility and ameliorate abnormal behaviors in adolescent offspring." (PMID 38129829, 2023). "Furthermore, the CXCL12/CXCR4 signaling pathway played an important role in the migration defects of interneurons which may contribute to the increased epilepsy susceptibility in adolescent offspring." (PMID 38129829, 2023). "Our findings demonstrate that maternal anesthesia impairs interneuron migration through the CXCL12/CXCR4 signaling pathway, and influences the interneuron properties, leading to the increased epilepsy susceptibility in adolescent offspring." (PMID 38129829, 2023). "In the epilepsy susceptibility test, overexpression of CXCL12 prolonged the latency and increased cumulative doses of PTZ to induce tonic-clonic seizures, rescuing the increased epilepsy susceptibility caused by prenatal sevoflurane exposure." (PMID 38129829, 2023). "We observed the upregulation of IL1β and CXCL12 in the early phase of KA-induced epilepsy and elevated levels of CCL5 at a later time point, compared with control animals." (PMID 35326336, 2022). "Here, we assessed the expression levels of CCL5, CXCL2 and CXCL12 in a KA-induced model of epilepsy." (PMID 35326336, 2022). "Previous studies have reported a role for the CXCL12/CXCR4 pathway in regulating spontaneous epileptiform discharges in epilepsy via modulation of adult neurogenesis of hippocampal dentate GCs9,10." (PMID 31672961, 2019). "Our hypothesis was mainly based on the reported role of CXCL12 (a ligand of CXCR7) in regulating hippocampal adult neurogenesis in an animal epilepsy model." (PMID 31672961, 2019). "Due to the close relationship among CXCL12, CXCR4, and CXCR714, we predicted that CXCR7 plays a role in regulating hippocampal adult neurogenesis in epilepsy." (PMID 31672961, 2019). "We found no significant changes in CXCR4, CXCL11, and CXCL12 expression levels in the hippocampus of mice with KA-induced epilepsy or in the brain tissues of patients with TLE." (PMID 31672961, 2019). "However, the expression patterns of CXCL12, CXCL11, CXCR4, and CXCR7 in epilepsy remain unclear." (PMID 31672961, 2019).
hyperlipidemia (6 papers, 2011 to 2025). "Compared to no therapy or low-dose statin therapy, treatment with high-doses of HMG-CoA reductase inhibitors is associated with decreased circulating CXCL12 levels in subjects with hyperlipidemia, and CXCL12 is strongly and inversely associated with statin dose." (PMID 23369699, 2012). "In addition, statins, which are used to treat hyperlipidaemia, cause a decrease in CXCL12 levels." (PMID 34494495, 2021). "Serum CXCL12 was found to be elevated in hyperlipidaemia patients, suggesting its role as a biomarker." (PMID 34494495, 2021).
influenza (6 papers, 2015 to 2019). An acute viral infection of the respiratory tract, occurring in isolated cases, in epidemics, or in pandemics; it is caused by serologically different strains of viruses (influenzaviruses) designated A, B, and C, has a 3-day incubation period, and usually lasts for 3 to 10 days. "In an influenza-infected mouse model, plerixafor treatment as well as genetic deletion of CXCL12 in neutrophils recapitulates the effect of neutrophil depletion on CD8+ T cell recruitment." (PMID 31174392, 2019). "We also observed that CXCL12 expression in neutrophil-derived microparticles at an early stage of influenza infection is critical for the CD8+ T cell-mediated immune response in mice." (PMID 30967528, 2019). "Neutrophils have also been demonstrated to influence CD8+ T cell migration into influenza-infected trachea via deposition of CXCL12 chemokine trails from blood vessels to the infected region." (PMID 28112242, 2017). "An example is during immune responses to influenza infection, whereby neutrophils deposit EVs on collagen tracks to release the chemokine CXCL12 slowly and thereby attract anti-influenza cytotoxic T lymphocytes." (PMID 27814025, 2017). "However, it was not previously determined if this CXCL-12 dependency would persist throughout all stages of influenza infection, including the formation and maintenance of local memory." (PMID 27741316, 2016).
leukocytosis (6 papers, 2013 to 2023). "Early studies using Cxcr4- or Cxcl12-deficient mice established the importance of HSPC maintenance of leukocytosis." (PMID 36821386, 2023). "Heparin-induced leukocytosis requires glucosamine 6-O-sulfation and is caused by blockade of L-selectin-mediated, P-selectin-mediated, and CXCL12-mediated leukocyte trafficking." (PMID 26742480, 2016). "Another study investigating the effects of the CXCL12–CXCR4 axis in a hypercholesterolemia mouse model using black 6 (BL6) mice and revealed that mice fed with high fat diet had higher levels of CXCL12 in their circulation along with leukocytosis." (PMID 33503867, 2021). "Administration of the CXCR4 antagonist AMD 3100 reversed this observation and led to a release of HSC progenitor cells from the bone marrow and fast generalized leukocytosis, demonstrating the importance of CXCL12 as a retention signal for HSC in the bone." (PMID 24040160, 2013). "Blocking CXCR4 with pharmacological agents disrupts CXCL12 signaling and leads to leukocyte release and increased white blood cell (WBC) count in peripheral blood (leukocytosis)." (PMID 29554149, 2018). "Under diabetic conditions in mice, decreased Cxcl12 expression (not Cxcr4) determines the primitive hematopoietic maintenance in the BM niche and indirectly affects leukocytosis in the circulation." (PMID 36821386, 2023).
meningioma (6 papers, 2012 to 2024). A generally slow growing tumor attached to the dura mater. "Some cytokines/chemokines, e.g., IL-6, CXCL12 and TGF-ß, show a formation of autocrine loops in meningioma cells." (PMID 34503077, 2021). "Indeed, a direct protective role of full length CXCL12 has been reported in meningioma and in a primary neuronal cell line without any involvement of inflammatory cells." (PMID 22675496, 2012).
Miscarriage (6 papers, 2017 to 2023). A pregnancy that ends at a stage in which the fetus is incapable of surviving on its own, defined as the spontaneous loss of a fetus before the 22th week of pregnancy. "To better understand the role of CXCL12/CXCR4 and EEC motility in pregnancy, in the future research, we may explore their relationship with implatation failure and miscarriage, which is beneficial to find a biological target for unexplained miscarriage." (PMID 32041571, 2020).
Myocardial fibrosis (6 papers, 2015 to 2026). "These cells interact with EndoCs, ECs, and macrophages through the Cxcl12-Ackr3, Ptn-Ncl, and Mdk-Lrp1 signaling pathways, thereby influencing myocardial fibrosis progression." (PMID 40595870, 2025). "Mice overexpressing CXCL12 had impaired cardiac function and increased myocardial fibrosis after MI, and high concentrations of CXCL12 can upregulate TNF-α protein to induce cardiomyocyte apoptosis." (PMID 35668739, 2021). "Interestingly, it has been shown that the increased levels of CXCL12α and the low HS binding isoform of CXCL12 participate in the kidney and myocardial fibrosis." (PMID 31533830, 2019).
pancreatic adenocarcinoma (6 papers, 2012 to 2024). "A recent study has proposed that the paucity of T cells observed in tumor islets of pancreatic adenocarcinoma was due to the presence of CXCL12 in cancer cell regions, creating a chemical barrier against T cells." (PMID 26528284, 2015). "The continuous expression of CXCL12 in neural cells and the high frequency of PNI in pancreatic adenocarcinoma prompted us to test the hypothesis that the CXCL12/CXCR4 signaling pathway is involved in PNI in PCa." (PMID 25605248, 2015). "The CXCL12/CXCR4 axis plays an important role in the progression and organ-specific metastasis of pancreatic adenocarcinoma." (PMID 23181100, 2012).
seminoma (6 papers, 2013 to 2023). A radiosensitive malignant germ cell tumor found in the testis (especially undescended), and extragonadal sites (anterior mediastinum and pineal gland). "Similarly to our results in stage I disease, CXCL12 expression was associated with a higher risk for disease recurrence in patients with metastatic non-seminoma after first line chemotherapy." (PMID 31412792, 2019). "As a conclusion of those contradictory results we currently discourage clinicians to use CXCL12 for clinical decision making until further studies clarify the role of CXCL12 in in stage 1 non-seminoma." (PMID 31412792, 2019). "However, all studies, including ours, demonstrate that CXCL12 is almost exclusively found in non-seminomas, and we confirmed this on an in silico analysis of The Cancer Genome Atlas (TCGA) database (p < 0.0001)." (PMID 32758242, 2020). "CXCL12 immunoexpression in tumor cells did not associate with relapse, but non-seminoma patients exhibiting vascular invasion and CXCL12-positive stromal/inflammatory cells showed significantly improved relapse-free survival (p = 0.015)." (PMID 32758242, 2020). "Indeed, we found that non-seminoma patients with CXCL12 positivity in surrounding stromal/immune cells showed a significantly improved relapse-free survival, which was able to discriminate two risk groups within patients showing vascular invasion (p = 0.015)." (PMID 32758242, 2020). "In patients with non-seminoma, CXCL12 expression was found in 52 patients (52.5%)." (PMID 31412792, 2019). "We were not able to show an association between CXCL12 and lower recurrence rates in stage I non-seminoma patients." (PMID 31412792, 2019). "However, in our analysis we were not able to confirm these findings of Gilbert and our analyses suggest that CXCL12 might even be a risk factor and not a protective factor in stage 1 non-seminoma." (PMID 31412792, 2019). "Exposure to CXCL12 induces an invasion response in the TCam-2 seminoma cell line, but not in non-seminoma cell lines (833ke and Ntera2/D1)." (PMID 36614308, 2023). "We have independently looked at the expression of CXCL12 and CXCR4 in TGCTs (McIver SC, Loveland KL, Roman SD, Nixon B, Kitazawa R, McLaughlin EA, unpublished observations) and confirmed that CXCR4 mRNA was overexpressed in seminomas." (PMID 24555040, 2013). "CXCL12 is exclusively expressed in non-seminoma and absent in seminoma, normal tissue or GCNIS." (PMID 31412792, 2019). "CXCL12 expression was absent in all seminomas but was found in 52 of 99 (52.5%) non-seminomas." (PMID 31412792, 2019). "In this study CXCL12 expression was observed in a large number of patients with non-seminoma but was absent in normal tissue, GCNIS or seminoma." (PMID 31412792, 2019). "Pure seminoma, GCNIS and adjacent normal testicular tissue are CXCL12 negative." (PMID 31412792, 2019). "CXCL12 expression was negative in normal tissue, GNCIS and seminoma tissue." (PMID 31412792, 2019). "Therefore the expression of CXCL12 and CXCR4 is more likely to be a better indicator of the possibility of seminoma metastasis rather than non-seminoma." (PMID 24555040, 2013).
vitiligo (6 papers, 2017 to 2025). Generalized well circumscribed patches of leukoderma that are generally distributed over symmetric body locations and is due to autoimmune destruction of melanocytes. "All 4 studies (177 vitiligo patients versus 82 controls) on circulating CXCL12 in vitiligo reported increased values in vitiligo patients compared to controls, resulting in a highly significant P-value of the meta-analysis (P = 0.003)." (PMID 36911664, 2023). "CXCL12 concentrations are also 1.2-1.7 higher in active vitiligo (2 studies; 45 active vs 65 stable)." (PMID 36911664, 2023). "A more recent study revealed that 5-fluorouracil (5-FU) significantly increased the CXCL12 level in the vitiligo skin, and blocking the CXCL12/CXCR4 pathway, in turn, inhibited melanocyte migration." (PMID 35096274, 2022). "The function of CXCL12 as an efficient predictor of vitiligo has also been confirmed in other studies." (PMID 35096274, 2022). "A recent study integrated genomics and proteomics to propose a series of potential drug targets and biomarkers, and CXCL12 was on the top of the listed secretary proteins in vitiligo." (PMID 35096274, 2022). "CXCL12 is elevated in the plasma of vitiligo patients compared to healthy controls (V-P:4707 ± 1378 pg/ml; Ctrl-P: 1274 ± 740.5 pg/ml, p = 0.03)." (PMID 35464413, 2022). "Compared with the healthy control, elevated CXCL12 was observed in the serum of vitiligo patients, with a higher secretion of CXCL12 in patients with progressive vitiligo." (PMID 35096274, 2022). "On the other hand, the prominent infiltration of CD11c+ CXCL12+ DCs was found in vitiligo-affected skin in the early stage of the disease." (PMID 35096274, 2022). "CXCL12 is one of the top secretary proteins upregulated in vitiligo." (PMID 36911664, 2023). "CXCL12 induces CXCL8 production which is also more pronounced in vitiligo patients." (PMID 36911664, 2023). "However, the levels of IFNG, PRF1, GZMB and CXCR3, CXCL9, CXCL10, CXCL12, and other cytokines also had an upward trend in the vitiligo group." (PMID 37207234, 2023). "Despite the possible role of upregulated CXCL12 in vitiligo activity and progression, studies also indicate that CXCL12 may also participate in these therapeutic trauma-induced skin repigmentation." (PMID 35096274, 2022). "It is hypothesized that under proper injury, the CXCL12-enriched microenvironment may favor melanocyte recruitment by trafficking corresponding melanocyte precursors into the perilesional and lesional vitiligo areas to induce therapeutic effects." (PMID 35096274, 2022). "Additionally, CXCL12 regulates the migration and differentiation of melanocyte precursors and may play a role in the repigmentation of vitiligo lesions." (PMID 36911664, 2023). "Studies examined patient-derived melanocytes and skin samples, and found a significant increase in the expression of epidermal melanocyte-derived CXCL12, surrounded by CXCR4+ cells in early vitiligo." (PMID 35096274, 2022). "show that CXCL12 and CCL5 are relevant to the recruitment of APCs in early vitiligo." (PMID 29238346, 2017). "ACKR3 (CXCR7) is another high-affinity receptor for CXCL12; however, there is a lack of investigations into ACKR3 in vitiligo up to date." (PMID 35096274, 2022).